TNF (tumor necrosis factor)
Diseases named in the same sentence as TNF in open-access papers (continued):
Sharing a sentence is not in itself a finding about the gene and the disease.
Arthritis (continued). "Studies in mice have also shown that BBR can improve the clinical symptoms of various types of arthritis by downregulating the expression levels of inflammatory factors, such as IL-1β, IL-6, and TNF-α." (PMID 40829428, 2025). "Intra-articular injection of DSCM-MSCs in TNF-α-induced arthritis models reduces synovial inflammation, suppresses expression of MMP13 and ADAMTS5, and preserves cartilage integrity." (PMID 40868398, 2025). "Gene expression intensities were much higher in the arthritis-affected rams than in the healthy ones for the genes IL-1α, IL-1β, IL-6, IL-10, TNFα, NCF4, NFKB, TMED, FCAMR, iNOS and COX18." (PMID 40005882, 2025). "Prediction was then extended to hindpaws (52.4% in test group) and forepaws from WT and tumor necrosis factor transgenic (TNF-Tg) mice with inflammatory-erosive arthritis of both sexes across age." (PMID 40654621, 2025). "QRHXD and MTX significantly reduced toe swelling and arthritis, decreased inflammatory factors such as IL-1β, IL-6, IL-17, and TNF-α, and increased the anti-inflammatory factor IL-10." (PMID 40124380, 2025). "The synergistic interplay of TNF-α, IL-6, and IL-1β establishes a self-amplifying inflammatory loop central to arthritis progression." (PMID 41583484, 2025). "siRNA targeting TNF-α has demonstrated efficacy in reducing synovial inflammation and cartilage erosion in preclinical arthritis models." (PMID 41425586, 2025). "We also determined the concentrations of the cytokines IL-6, IL-10, IFNγ, TNFα, IL-17A, IL-17F, and IL-22 in serum samples of the arthritis patients." (PMID 40806470, 2025). "We demonstrate that physiological shear stress protects the CMC against TNF‐α‐mediated arthritis, similar to the in vivo situation." (PMID 39716911, 2025). "In vivo, after treatment with LNP-siTNF-α-HCQ, the paw volume, arthritis scores, and plasma TNF-α content of the established arthritis model rats were significantly lower than those of the control group." (PMID 39861693, 2025). "The NRF2 inducer sulforaphane was demonstrated to have an anti-arthritis effect by inhibiting PC differentiation and production of inflammatory cytokines (IL-6, IL-17, TNFα etc.)." (PMID 39875809, 2025). "When comparing healthy rams to those with arthritis, the expression levels of the following genes were noticeably higher: IL-1α, IL-1β, IL-6, IL-10, TNFα, NCF4, NFKB, TMED, FCAMR, iNOS and COX18." (PMID 40005882, 2025). "Specifically, treatment reduced arthritis scores, decreased TNF-α levels in synovial fluid, lowered pro-inflammatory cytokine release, and effectively protected cartilage and bone from destruction compared with control formulations." (PMID 41425586, 2025). "In WT arthritis mice, the serum contents of TNF‐α and IL‐6 decreased with CEL treatment; the IGF2BP3 KO group and the IGF2BP3 KO plus CEL group presented the same trend." (PMID 41164801, 2025). "Complete A20 deficiency (A20-/-) in mice results in severe multi-organ inflammation, cachexia, and destructive arthritis, culminating in neonatal lethality within two weeks due to hypersensitivity to lipopolysaccharide (LPS) and TNF." (PMID 41583484, 2025). "This reduction highlights NTZ’s ability to suppress TNF-α, a key mediator in arthritis inflammation." (PMID 40191469, 2025). "This concept is supported by experimental evidence in murine models of chronic inflammatory arthritis using TNF transgenic mice, inhibiting lymphatic drainage significantly exacerbated arthritis severity." (PMID 41227037, 2025). "Splice-switching oligonucleotides (SSOs) promote exon 7 skipping in TNFR2 mRNA and upregulate soluble TNFR2 isoform, which blocks TNF signaling and reduces inflammation in the arthritis model." (PMID 40007754, 2025). "By 12 weeks, Irg1−/−/TNF-Tg mice exhibited significantly higher arthritis scores, more severe hind paw swelling, and greater paw thickness." (PMID 40500265, 2025).
Arthritis (continued). "SKG mice, which exhibit arthritis along with high levels of TNF-α after intraperitoneal injection of curdlan, were generated and then intravenously injected with OE-NC MSCs or OE-HDAC5 MSCs." (PMID 41436435, 2025). "Previous work demonstrated that a NOTCH2 gain-of-function mutation sensitizes mice to the development of arthritis following DMM surgeries and to the osteolytic actions of TNFα." (PMID 40345585, 2025). "These flavonoids demonstrate potent anti-inflammatory properties by inhibiting prostaglandin E2 synthesis and modulating cytokines like TNF-α and IL-6, offering promise for chronic inflammatory conditions such as arthritis." (PMID 40870742, 2025). "It is expressed in high levels in Th1 effector memory cells in inflamed joints and limits the expression of interferon-γ, IL-2, and TNF-α and ameliorates Th1-mediated immunopathology in antigen-induced arthritis." (PMID 40761796, 2025). "The Soufeng sanjie formula (centipede, scorpion, and additional herbs) likewise ameliorated arthritis by decreasing IL-6, TNF-α, and IL-17 and reestablishing the Th17/Treg balance." (PMID 40423312, 2025). "As shown by 2 independent studies on CIA or TNF-α transgenic arthritis mouse models and on postmortem brain tissue from people with RA, microglia per se exhibit an inflammatory transcriptomic phenotype during active disease." (PMID 40638239, 2025). "In TNF-transgenic mice exhibiting advanced arthritis, anti-TNF therapy significantly reduces synovitis and restores lymphatic contraction." (PMID 40496852, 2025). "Intra-articular delivery of DSCM-expanded MSCs in TNF-α-induced arthritis models reduces synovial thickness, inflammatory cytokines, and ECM degradation." (PMID 40868398, 2025). "Arthritis symptoms were improved in mice with collagen-induced arthritis when administered daptomycin, and the serum levels of IL-1β, TNF-α, and IL-6 were decreased." (PMID 41226564, 2025). "IL-17and TNF-α are two key pro-inflammatory cytokines that play critical roles in the pathogenesis of various inflammatory and autoimmune diseases, including arthritis." (PMID 39687160, 2024). "These inflammatory markers also correlate with SLEDAI-2K, levels of dsDNA (CCL2, CXCL10), the presence of lupus nephritis (CCL2, CXCL10, and TNF-α), and arthritis (IL6)." (PMID 38881906, 2024). "For example, the identification of TNF as a therapeutic target emerged from positive clinical experiences with IL receptor antagonists and the effects of anti-TNF antibodies in animal models of arthritis." (PMID 39600762, 2024). "IL‐10 suppresses the production of inflammatory mediators, including IL‐1β and TNF‐α, reducing the intensity of inflammatory reactions and alleviating symptoms and inflammation in arthritis." (PMID 39554315, 2024). "Our finding that CRP prevented rise in the serum level of IL-17 suggests that IL-17 is more critical than TNF-α for the initiation of the development of arthritis." (PMID 38650931, 2024). "Tumor necrosis factor alpha (TNF-α), a key mediator of inflammation in arthritis, fosters the dynamic regulation of O-GlcNAcylation during osteoclastogenesis." (PMID 38773637, 2024). "The molecular docking results shed light on the potential binding affinities of these compounds with key inflammatory targets involved in arthritis, specifically TNF-α and IL-6." (PMID 38817355, 2024). "TNF-α stimulates the secretion of metalloproteinases, enzymes which degrade surrounding tissues in cases of arthritis." (PMID 39687160, 2024). "Pcopri can inhibit the onset of arthritis by stimulating Th1 cells and reducing Th17 response and inflammatory cytokines (i.e., IL-2, IL-17, and TNF-α), thereby treating RA." (PMID 39484157, 2024). "In the case of arthralgia or arthritis predominance, TNF inhibitors are preferred as second-line medications, but they are ineffective for HLH." (PMID 39335580, 2024).
Arthritis (continued). "Studies in patients with arthritis showed that W-BC helped reduce inflammatory markers such as IL-6, tumor necrosis factor, and serum CRP." (PMID 39576692, 2024). "Recent research indicates that buckwheat flavonoids regulate the expression of pro-inflammatory factors (e.g., IL-6, TNF-α), suppress inflammatory responses, and offer therapeutic potential for conditions such as arthritis and cardiovascular disorders." (PMID 39767010, 2024). "Limited trials of TNFα inhibitors in CGD patients have shown effectiveness in the treatment of arthritis, bowel fistulas and reducing the symptoms of interstitial bowel disease, a frequent inflammatory complication in this population." (PMID 38404573, 2024). "Collectively, our results show that SF-Cyld controls TAK1 kinase to prevent IKK2 and NF-κB hyperactivation but not Ripk1-mediated death, leading to deterioration of arthritic phenotype in TNF-dependent arthritis." (PMID 39122678, 2024). "Early studies in our lab established that TNF targeting of TNFR1 on synovial fibroblasts (SFs) is required for the development of arthritis and suffices to orchestrate full pathogenesis." (PMID 39235454, 2024). "CFA-induced arthritis significantly upregulated the serum levels of cytokines, including TNF-α and IL-6, accompanied by an elevation in circulatory inflammatory cells, which can be confirmed through the increased weight of the thymus and spleen." (PMID 39741627, 2024). "The main mediators identified in arthritis are tumor necrosis factor-alpha (TNF-α), cytokines IL-1, IL-6 and IL-8 and matrix metalloproteinases (MMPs)." (PMID 39273351, 2024). "In vivo experiments confirmed the favorable effects of quercetin in CIA rats, including an improved arthritis score and reduced ankle bone destruction, in addition to a decrease in the pro-inflammatory cytokines IL-1β, IL-6, IL-17, and TNF-α in serum." (PMID 39390367, 2024). "In this study, we pursued το decouple the CYLD involvement in the inflammatory behavior of SFs, by employing both acute and chronic TNF-dependent modeled arthritis, coupled with genetic targeting and biochemical studies on DUB-deficient Cyld SFs." (PMID 39122678, 2024). "In this model, osteostatin reduced the local production of the pro-inflammatory cytokines IL-1β, IL-6, IL-17, and TNF-α, which are increased in patients with arthritis and enhanced the release of the anti-inflammatory cytokine IL-10." (PMID 38474000, 2024). "Tumor necrosis factor-alpha (TNF-α) and interleukin-6 (IL-6) are cytokines that play pivotal roles in inflammatory processes, including those associated with arthritis." (PMID 38817355, 2024). "The first human antibody Adalimumab (Humira) using phage display technology was approved in USA in 2002 for the treatment of arthritis and Crohn’s disease which inactivates tumor necrosis factor-alpha (TNF-α)." (PMID 38216921, 2024). "Elevated expression levels of TNF and IL-17 have been detected in various chronic inflammatory bone diseases, including arthritis, osteoporosis, periapical periodontitis, and periodontal disease." (PMID 40225753, 2024). "The IDM DMN treatment effectively reduced arthritis severity, resulting in decreased paw swelling, arthritis index, spleen hyperplasia, and serum IL-1β and TNF-α levels." (PMID 39771485, 2024). "The datapoints have been revisualized for comparison with other bones or TNF-Tg mice with inflammatory-erosive arthritis as outcomes relevant to the current work." (PMID 38968295, 2024). "Mice with disrupted Zfp36 expression have been shown to develop severe arthritis, autoimmunity, cachexia, dermatitis, and myeloid hyperplasia, due to the overexpression of TNF-α." (PMID 39684798, 2024). "The administration of an anti-TNF mAb prevented the development of IL-23-driven arthritic pain and reduced arthritis severity." (PMID 39107827, 2024).
Arthritis (continued). "Plant extracts can alleviate the symptoms of arthritis by inhibiting the expression of inflammatory factors such as IL-6 and TNF-α in a rat ankle arthritis model." (PMID 39220949, 2024). "For example, vaccination with TNFα displayed on L1 VLPs induced high-titer (> 104) anti-TNFα antibody that prevented collagen-induced arthritis in a mouse model." (PMID 38225646, 2024). "For example, neutralization of TNF can begin to reduce pain in experimental arthritis and in patients within one day." (PMID 39596013, 2024). "Clinical studies have showed that blocking either IL-17 or TNF-α individually can lead to some improvement in arthritis symptoms." (PMID 39687160, 2024). "The inhibition of Hh signaling in rats with arthritis using cyclopamine, another inhibitor of Shh, reduced the expression of TNFα, IL-1β, and IL-6." (PMID 38668020, 2024). "Later studies found that even the membrane-bound form of TNF-α (mTNF-α) can lead to the full expression of arthritis." (PMID 39636801, 2024). "Arthritis-related inflammation generates pro-inflammatory cytokines such as TNF-α, IL-6, and interleukin (IL)-1β." (PMID 39458926, 2024). "For example, certain cytokines such as interleukin-1β (IL-1β), tumor necrosis factor-α (TNF-α), and interleukin-6 (IL-6) have been identified as key regulators in OA development and arthritis inflammation." (PMID 38496843, 2024). "In a study in rats in a collagen-induced arthritis model, Pf-06650833 inhibited serum TNF-α production in response to LPS by 87% at a dose of 30 mg-kg−1." (PMID 39137914, 2024). "Our findings suggest that UA has potential as a binding target for TNF, suppresses inflammatory cytokines in PBMCs, and exhibits anti-inflammatory effects on arthritis in a mouse model." (PMID 39691400, 2024). "Antibodies targeting IL-19 have prevented arthritis and osteolysis in animal models by diminishing the secretion of pro-inflammatory cytokines, including TNF-α, IL-1β, IL-6, and RANKL." (PMID 39104791, 2024). "Our prior work has focused on assessment of arthritis progression using the well-characterized tumor-necrosis factor transgenic (TNF-Tg) murine model of RA." (PMID 38968295, 2024). "We found that there was a large amount of TNF-α in arthritis induced by LPS in mice with MTX treatment and with saline treatment, but much less TNF-α in arthritis induced by LPS in mice with DXM and combined therapy of DXM and MTX." (PMID 39510764, 2024). "In-vivo efficacy studies using CFA-prompted arthritis in rodents showed a critical expansion in body wt and an undeniable reduction in paw thickness, paw volume, and TNF-α treated with BSEN compared to the arthritis control and BSE-treated group." (PMID 39668885, 2024). "Leukotriene B4 (LTB4) is an important inflammatory lipid mediator that mediates or exacerbates synovial inflammation in the K/BxN arthritis model, and TNF stimulates the production of high levels of leukotriene B4 in FLS." (PMID 38482018, 2024). "Acid-activatable curcumin polymer micelles significantly protect joint structures from arthritis by inhibiting TNF-α and IL-1β." (PMID 37938371, 2024). "IFN‐γ can stimulate inflammatory cells to produce inflammatory mediators responsible for arthritis symptoms, such as TNF‐α, IL‐1, and various chemokines." (PMID 39554315, 2024). "TNF-a has been identified as a proinflammatory cytokine with a central role in arthritis, which was further proved by the clinical efficacy of the TNF-α inhibitions therapy in JIA." (PMID 39185410, 2024). "plant can also reduce paw and inflammatory swelling, the arthritis index, and TNF-α and IL-1β and increase the production of serum IL-10 in Freund’s complete adjuvant-induced arthritis model in rats." (PMID 38794160, 2024). "Research has shown that campesterol is a good therapeutic option for arthritis, as it reduces paw edema in rats and lowers the levels of inflammation-inducing cytokines, such as IL-1, TNF-α, NFκ-B, IL-6, and COX-II." (PMID 39459282, 2024).
Arthritis (continued). "At this point, recommendations by the American College of Rheumatology/Arthritis Foundation Guidelines (ACR/AFG) suggest initiating therapy with a monoclonal antibody TNF-alpha inhibitor such as ADA." (PMID 39254907, 2024). "Our results identify SF-Cyld as a regulator of TNF-mediated arthritis and inform the signaling landscape underpinning the SF responses." (PMID 39122678, 2024). "In AIA mice, IDM-MMs-loaded DMNs significantly reduced arthritis severity, including paw edema, arthritis index, spleen hyperplasia, and serum levels of IL-1β and TNF-α." (PMID 39771485, 2024). "Conversely, the induction of arthritis in mice (model group) resulted in a significant increase in the levels of IL‐6, IL‐1β, and TNF‐α cytokines in the ankle joint tissue (p < .05)." (PMID 39554315, 2024). "Further, in models of Freund’s adjuvant-induced complete arthritis or collagen-induced arthritis in rodents, andrographolide has decreased the clinical score of arthritis and joint damage, as well as NO and TNF-α production." (PMID 39061498, 2024). "Here, we investigated the role of Lyp in TNFα-induced priming of neutrophil ROS production and in the development of arthritis using new selective Lyp inhibitors." (PMID 39724988, 2024). "In this paper, plasma of RA patients, the tumor necrosis factor-alpha-induced human synovial fibroblasts, and an animal model of arthritis induced by collagen were applied to initially inquire about the therapeutic effect of ferroptosis." (PMID 39624162, 2024). "Patients with arthritis have abnormal serum cytokine concentrations, such as tumor necrosis factor-α (TNF-α), IL-1, and IL-17, compared with healthy individuals." (PMID 39286809, 2024). "It is a novel peptide inhibitor for TNFα that effectively inhibits its activity and shows strong potential for anti-arthritis drug development." (PMID 38839973, 2024). "TNF-α is an important molecule in RA, as mice that overexpress human TNF-α rapidly and spontaneously develop severe arthritis." (PMID 39339815, 2024). "In TNF-Tg male mice with severe arthritis, the talus and calcaneus exhibited the most sensitive response to anti-TNF therapy measured by effect size of bone volume change over treatment period." (PMID 38968295, 2024). "TNF- α and IL-6 pro-inflammatory cytokine expressions were significantly increased when arthritis developed in all arthritic-induced rat groups compared to Normal control (P<0.05)." (PMID 39055869, 2024). "To evaluate the mesenchymal-specific contribution of Cyld in regulating the TNF-modeled arthritis, we generated mice of the hTNFTg CyldM-Δ9/Δ9 genotype." (PMID 39122678, 2024). "Previous studies have demonstrated that IL-17 C induces elevated levels of TNF-α and aggravates arthritis in CIA mice, and is positively correlated with the degree of inflammation and disease activity." (PMID 38413973, 2024). "Irradiation of 0.1 sub-THz alleviated arthritis symptoms and reduced the expression of several pivotal proinflammatory cytokines, including IL-6, TNF-α, IL-1b, and IL-17 in CIA mice." (PMID 38892148, 2024). "IL‐6, IL‐1β, and TNF‐α cytokine levels, on the other hand, significantly increased in the ankle joint tissue when arthritis was induced in mice (model group) (p < .05)." (PMID 39479687, 2024). "There has also been a further example of an arthritis sufferer developing T1D after beginning anti-TNFα therapy." (PMID 37483613, 2023). "Hess and colleagues have recently demonstrated that both mice with TNF-α-mediated arthritis and humans with RA show enhanced brain activity in the centers involved in pain perception and the control of emotions." (PMID 37568441, 2023). "We show that LXA4 reduced TNF-α, IL-1β, and IL-6 levels and increased IL-10 levels in TiO2-induced arthritis." (PMID 37388729, 2023).